IL1A (interleukin 1 alpha)
Diseases named in the same sentence as IL1A in open-access papers (continued):
Sharing a sentence is not in itself a finding about the gene and the disease.
type 1 diabetes (6 papers, 2016 to 2022). "In adults with type 1 diabetes, we found that the inflammatory cytokines IL-1α, IL-4, IL-12p70, TNF-α, and the adhesion molecule E-selectin were inversely associated with 24-hour-derived HRV parameters after adjustments for age, sex, disease duration, and smoking." (PMID 32908447, 2020). "IL1A or IL-1 (BCT1D = 60.7; BChealthy = 0) is a pro-inflammatory cytokine that takes part in the “diabetes type I pathway”." (PMID 27257970, 2016).
acute kidney injury (5 papers, 2016 to 2023). Sudden and sustained deterioration of the kidney function characterized by decreased glomerular filtration rate, increased serum creatinine or oliguria. "The mRNA abundance of cytokines (IL-1α, IL-1β, IL-8, IL-10, TNF-α, TGF-β) and enzymes (5-LO, iNOS) was measured prospectively in blood leukocytes from 34 dogs with severe leptospirosis and acute kidney injury, including 22 dogs with leptospirosis-associated pulmonary hemorrhages." (PMID 26824356, 2016). "G. vaginalis-exposed mice displayed higher levels of IL-1α, IL-1β, TNF-α, MIP-1β, and IL-2 in the kidney and higher levels of serum creatinine, a biomarker of acute kidney injury, than PBS controls." (PMID 28358889, 2017).
ameloblastoma (5 papers, 2017 to 2024). The most common odontogenic tumor, arising from the epithelial component of the embryonic tooth and usually affecting the molar-ramus region of the mandible or maxilla. "The highest and lowest IL-1α levels in the cystic fluid of 11 patients with ameloblastoma were 1.694 pg/mL and 0.2354 pg/mL, with an average of 0.9227 pg/mL." (PMID 36055803, 2022). "Several studies reported that some cytokines were secreted from ameloblastoma cells, including IL-1α, IL-1β, IL-6, and TNF-α." (PMID 35243014, 2022). "Previously we established a follicular ameloblastoma cell line (AM-3) and AM-3 highly expressed IL-1α." (PMID 35243014, 2022). "We previously reported that the productions of IL-6 and IL-8 were induced in stromal fibroblasts stimulated with AM-3 ameloblastoma-derived IL-1α." (PMID 35243014, 2022). "Our group recently determined that interactions between ameloblastoma tumor cells and stromal fibroblasts are often conveyed by various cytokines including interleukin (IL)‐1α, IL‐6, and IL‐8, which create a microenvironment favorable to tumor invasion." (PMID 29226086, 2017).
amyotrophic lateral sclerosis (5 papers, 2018 to 2025). Amyotrophic lateral sclerosis (ALS) is a neurodegenerative disease characterized by progressive muscular paralysis reflecting degeneration of motor neurons in the primary motor cortex, corticospinal tracts, brainstem and spinal cord. "To illustrate, knockout of microglial-derived IL-1α, TNF-α, and C1q—pro-inflammatory astrocytic activators—in a genetic mouse model of amyotrophic lateral sclerosis (ALS) increased animal life span and improved peripheral nerve fiber formation when compared to control." (PMID 37238617, 2023).
bacterial vaginosis (5 papers, 2015 to 2024). Infection caused by bacterial overgrowth in the vagina. "The diversity of microbial communities dominated by bacteria associated with bacterial vaginosis leads to an increase in the levels of cytokines, such as IL-8, IL-1a, IL1b, interferon and tumor necrosis factor." (PMID 35359942, 2022). "For example, IL-1α, IL-1β, and tumor necrosis factor-α, along with bacterial vaginosis, may be associated with genetic polymorphisms in the innate immune Toll-like-receptor (TLR1, TLR 2, TLR 4 and TLR 9) and proinflammatory cytokines (IL-1β, IL-1ra, IL-6, IL-6, CXCL8, and IL-10)." (PMID 35359942, 2022). "Our in vivo experiments demonstrate that G. vaginalis may induce significant inflammatory responses within 24 h, characterized by the release of proinflammatory cytokines IL-1α and IL-1 β at levels similar to those seen in bacterial vaginosis." (PMID 39598357, 2024). "Finally, we did not obtain test results for lower genital tract microbiology, even though it may affect the CVF VDBP level according to a reported positive correlation between bacterial vaginosis and IL-1α and IL-1β levels." (PMID 29879190, 2018). "In cross-sectional studies, women with bacterial vaginosis (BV) and/or more diverse, non-Lactobacillus dominant communities consistently had higher concentrations of IL-1β and IL-1α than women without BV, with consistently decreased IP-10 concentrations." (PMID 36303630, 2022).
cardiac hypertrophy (5 papers, 2015 to 2024). "Histochemistry on heart sections showed that H3LOE induced cardiac hypertrophy, which was also attenuated by IL1A-blocking antibody." (PMID 39168969, 2024). "Cardiac-specific overexpression of human interleukin 1α (IL-1α) results in cardiac hypertrophy, and systemic administration of IL-1β antibodies or IL-1β deletion prevents aortic banding-induced hypertensive cardiac hypertrophy." (PMID 32831633, 2020). "Moreover, Akt activation promotes TNF-α-induced elevation in mRNA levels of IL-6, IL-1α, and IL-1β in cardiac fibroblasts and cardiac hypertrophy in primary cardiomyocytes." (PMID 32831633, 2020).
cyst (5 papers, 2018 to 2024). A sac-like closed membranous structure that may be empty or contain fluid or amorphous material. "On the other hand, IL-1α and IL-1β levels in the cyst group were as low as those in the control group in the present study." (PMID 30012121, 2018). "We measured the intracapsular pressure and IL-1α concentration in the cyst fluid." (PMID 36055803, 2022). "ELISA results showed that IL-1α and TNF-α were high inPseudomonas-positive cyst fluids, suggesting that the proinflammatory response created by macrophages might be induced in response toPseudomonas bacteria." (PMID 35538039, 2022). "According to our results,Pseudomonas exacerbates the pathogenesis by increasing the productions of TNF-α, IL-1α, BCL-2 and Ki-67, suggesting that this facultative anaerobic bacterium may trigger the pathogenesis of cyst formation." (PMID 35538039, 2022).
E. coli infection (5 papers, 2020 to 2025). "Take it together, IL-1α prevented E. coli infection by enhancing the killing ability of transendothelial neutrophils, while LPS destroyed it." (PMID 32733891, 2020). "Therefore, we also investigated the transcriptional changes in interleukin-family genes and found that E. coli infection significantly increased the expressions of IL-1α, IL-11, NFIL-3, IL-16, and other cytokines." (PMID 36876070, 2023). "In a mouse model for S. aureus and E. coli infections, animals with E. coli infection showed significantly greater serum levels of the cytokines interleukin (IL)-1α, IL-1β, IL-6, monocyte chemotactic protein (MCP)-1, and macrophage inflammatory protein (MIP)-1α than S. aureus-infected mice." (PMID 34247606, 2021).
glomerulonephritis (5 papers, 2023 to 2025). A renal disorder characterized by damage in the glomeruli. "Although IL-1α in LN has received limited attention it has been reported to contribute to glomerulonephritis in mice." (PMID 40166657, 2025). "Podocytes have been demonstrated to be the primary producers of IL-1α and IL-1β in humans and experimental models of glomerulonephritis." (PMID 38672094, 2024).
lung adenocarcinoma (5 papers, 2022 to 2025). A carcinoma that arises from the lung and is characterized by the presence of malignant glandular epithelial cells. "To re-program normal fibroblasts into CAFs, HFL1 cells were either treated with TGFβ1 (myCAFs), or with IL1α to activate them into iCAFs, or were co-cultured with the lung adenocarcinoma cells." (PMID 36635266, 2023). "IL1A is linked to a poor prognosis in lung adenocarcinoma (LUAD), unlike IL1B, indicating a potential role of IL1A in promoting LUAD tumor progression." (PMID 40612864, 2025).
lymphoma (5 papers, 2012 to 2023). A malignant (clonal) proliferation of B- lymphocytes or T- lymphocytes which involves the lymph nodes, bone marrow and/or extranodal sites. "We further identified the 3′-UTR of the IL1A gene as a potential target for miR-142-3p, miR-181a and miR-181b which are repressed in EBV-associated lymphomas." (PMID 22870299, 2012). "In a mouse model of intraperitoneal injection of necrotic lymphoma cells or acetaminophen-induced liver injury, neutrophil recruitment to the peritoneal cavity or liver was mediated by IL-1α alone or both IL-1α and IL-1β, respectively." (PMID 23209417, 2012). "In lymphomas, IL-1α may have anti-tumoral properties, whereas IL-1β has been shown to be expressed in HL cells from areas of tissue with active fibrosis, and the receptor IL-1R2 may contribute to local and systemic modulation in the disease." (PMID 36555171, 2022). "Taken together, these findings identify IL-15 and IL-1α as therapeutic targets in lymphoma." (PMID 24416335, 2014). "The up-regulation of IL1A in the EBV-positive as compared to the EBV-negative lymphomas might be explained by the ability of the pro-inflammatory cytokine to act as an auto- or paracrine growth factor and as an inhibitor of apoptosis." (PMID 22870299, 2012). "Concomitant with the decrease in miR142-3p, the mRNA levels for IL1A were up-regulated in EBV-positive lymphomas and we could indeed prove that the IL1A 3′-UTR contains a binding site for this miRNA." (PMID 22870299, 2012). "We determined the relative levels of miR-142-3p and IL1A in the EBV-positive vs. -negative lymphomas and found an inverse relationship pointing at an effect of this miRNA vis-à-vis the IL1A 3′-UTR." (PMID 22870299, 2012).
myocarditis (5 papers, 2017 to 2022). Myocarditis is a condition that is characterized by inflammation of the heart muscle (myocardium). "In particular, IL-1α profoundly influences the immune response that leads to myocarditis as it is released from dying myocardium cells." (PMID 36005648, 2022). "In myocarditis, IL-1α is released from the dying myocardium together with debris and other inflammatory mediators, and these in turn activate the inflammasomes in nearby cells." (PMID 29951067, 2018). "Both IL-1α and IL-1β have been shown to induce myocarditis and aneurysm formation in Lactobacillus casei cell-wall extract mouse model of KD; both being successfully improved with IL-1 blockade treatment such as anakinra." (PMID 28400731, 2017).
oral squamous cell carcinoma (5 papers, 2015 to 2025). "This study aimed to investigate the clinical significance of IL-1α expression in oral squamous cell carcinoma (OSCC), with a specific focus on its role in modulating cancer cell phenotype." (PMID 40940885, 2025). "This study is aimed at investigating the prognostic value of nuclear and cytoplasmic immunohistochemical IL-1α expression in oral squamous cell carcinomas (OSCCs)." (PMID 31320902, 2019).
osteoporosis (5 papers, 2010 to 2026). A condition of reduced bone mass, with decreased cortical thickness and a decrease in the number and size of the trabeculae of cancellous bone (but normal chemical composition), resulting in increased fracture incidence. "Cytokines other than RANKL and OPG, such as interleukin (IL)-1α, IL-6 and tumor necrosis factor-α, that are largely recognised as important effectors in the pathogenesis of several forms of osteoporosis, could have a role in TM-related osteoporosis." (PMID 29991466, 2019). "Importantly, the osteoporosis-related phenotype resulting from muscle Bmal1 knockout or aging was alleviated by nighttime time-restricted feeding (TRF), which reestablished a feeding-driven diurnal variation in Hmox1 expression within the muscle and reduced serum IL-1α levels." (PMID 42259765, 2026). "We studied the IL-1α (-889C/T), IL-1β (-511C/T) and the 86 base pair variable number tandem repeat (VNTR) in intron 2 of the IL-1 receptor antagonist (IL-1ra) gene in 117 postmenopausal women with osteoporosis and 135 control subjects without a history of symptomatic osteoporosis." (PMID 20940514, 2010).
papilloma (5 papers, 2010 to 2025). A benign epithelial neoplasm that projects above the surrounding epithelial surface and consists of villous or arborescent outgrowths of fibrovascular stroma. "Upregulation of CD26 also occurs in response to epidermal IL1α and wounding but is downregulated in the stroma of papillomas and SCCs." (PMID 26771241, 2016). "Using pentoxifylline, which was shown to inhibit TNF and IL-1a gene expression, the growth of DMBA/TPA induced papillomas were inhibited." (PMID 27389279, 2016). "On the other hand, K14.IL-1α transgenic mice more rapidly develop carcinomas de novo without going through a papilloma stage using a complete carcinogenesis protocol." (PMID 21297902, 2010). "IL-1α and IL-1Ra proteins are expressed primarily in the non-proliferating suprabasal layers of the epidermis and papillomas, with IL-1Ra expression up-regulated in papillomas and carcinomas compared to normal skin." (PMID 21297902, 2010).
rectal cancer (5 papers, 2014 to 2025). A primary or metastatic malignant neoplasm that affects the rectum. "Our group has recently unraveled the critical role of inflammatory cancer-associated fibroblasts (iCAFs) and interleukin 1α (IL1α) signaling in therapy resistance, employing a murine rectal cancer model and patient-derived tumor organoids (PDO)." (PMID 35449546, 2022). "Several cytokines, including interleukins and interferons, and other mediators of inflammation were associated with both colon (INFGR1, IL6, IRF2, NFκB1A, TLR2) and rectal cancer survival (IL1A and IL3), as was suppressor of cytokine signaling (SOCS1)." (PMID 25541970, 2014). "Our group could recently demonstrate the critical role of CAFs in mediating therapy resistance upon tumor-derived IL-1α signaling in a murine rectal cancer model or PDOs." (PMID 35449546, 2022).
septic shock (5 papers, 2015 to 2023). Shock caused by infection; frequently caused by gram negative bacteria, although some cases have been caused by other bacteria, viruses, fungi, and protozoa; characterized by fever, chills, tachycardia, tachypnea, and hypotension. "Moreover, Nlrp3+/+ mice injected with LPS displayed a mild systemic inflammatory response characterized by increased concentrations of specific chemokines and cytokines, including IL-1α and TNF, the latter being the prime mediator of the inflammatory response observed in septic shock." (PMID 35993366, 2022).
systemic candidiasis (5 papers, 2014 to 2023). "In systemic candidiasis, for example, IL-1α increases leukocyte antifungal activity, while IL-1β recruits neutrophils." (PMID 31425553, 2019). "The components of the NLRP3 inflammasome as well as IL-1β, IL-18, and the IL-1α/IL-1β receptor IL-1RI, are important for host survival from systemic candidiasis and prevention of dissemination of oropharyngeal candidiasis." (PMID 24967821, 2014).
uveitis (5 papers, 2009 to 2023). An inflammatory process affecting a part of or the entire uvea. "Interleukin-1 alpha, interleukin-1 beta, and tumor necrosis factor are shown to be associated with endotoxin-induced uveitis." (PMID 36157069, 2022). "Experimental uveitis was induced by intravitreal injection of IL-1α (10 ng) in New Zealand white rabbits." (PMID 19693263, 2009). "After 100 days, experimental uveitis was induced by an intravitreal injection of IL-1α in the eye." (PMID 19693263, 2009). "The histological findings demonstrated that experimental uveitis could be induced by intravitreal injection of IL-1α and that the uveitis subsided within 15 days." (PMID 19693263, 2009). "Ten days later, experimental uveitis was induced by intravitreal injection of IL-1α." (PMID 19693263, 2009). "The production of inflammatory cytokines induced by HTLV-1-infected T cells, such as IL-1α, IL-2, IL-3, IL-8, IL-10, TFN-α and GM-CSF, produces an intraocular inflammatory environment in patients with uveitis." (PMID 37605273, 2023).
vitiligo (5 papers, 2016 to 2025). Generalized well circumscribed patches of leukoderma that are generally distributed over symmetric body locations and is due to autoimmune destruction of melanocytes. "The serum concentrations of IL-1α and IL-33 were reported higher in vitiligo patients than that in healthy subjects." (PMID 36569840, 2022). "We have explored the role of Interleukin (IL)-1 in vitiligo by monitoring the expression of IL1A, IL1B, IL1Receptor1 (R1) and IL1 Receptor Antagonist (RN) in skin samples, effect of IL1-α on melanocyte viability, IL1R1 membrane expression and genotyping of IL1RN VNTR in Gujarat population." (PMID 27454254, 2016). "Our ROC analysis revealed that serum IL-1α, S100B, S100A9, and HMGB1 had predictive capacity on the diagnosis of vitiligo." (PMID 36569840, 2022). "For vitiligo diagnosis, S100B had the highest sensitivity (92.31%), whereas HMGB1 had the highest specificity (85.71%); the combination of IL-1α, S100B, S100A9, and HMGB1 increased the AUC value to 0.925, with a sensitivity of 87.50% and a specificity of 85.71%." (PMID 36569840, 2022). "It has already been reported that both TNF-α and IL-1α are increased in non-segmental vitiligo lesions." (PMID 31505868, 2019). "Another hypothesis is that HLA-G expressed on the skin of vitiligo patients interacts with KIR2DL4 receptors from NK cells, and this interaction may induce the production of proinflammatory cytokines such as IFN-γ, TNF-α, IL-1α, IL-1β, IL-6, and IL-8." (PMID 31505868, 2019). "Thus, to verify if Ins and IGF-1 evoke a pro-inflammatory feature in vitiligo keratinocytes and the possible role in immunopathogenesis, we quantified the amount of several secreted interleukins that demonstrated increased quantities of CXCL10, IL-6, IL-8, IL-1α, IL1-β, and TNFα." (PMID 40277891, 2025). "Therefore, in this study we would like to detect the serum expression of these alarmins (HMGB1, S100B, IL-1α, IL-33, S100A9, and S100A12) in NSV patients and healthy controls, to further investigate their clinical significance in the diagnosis and assessment of disease activity/severity in vitiligo." (PMID 36569840, 2022).
acute respiratory distress syndrome (4 papers, 2019 to 2024). Progressive and life-threatening pulmonary distress in the absence of an underlying pulmonary condition, usually following major trauma or surgery. "In a cohort of 35 acute respiratory distress syndrome (ARDS) and 13 sepsis patients, 3 patients showed anti-IL-6 auto-antibodies, two anti-IFNω auto-antibodies, two anti-IFNγ auto-antibodies, and one anti-IL-1α auto-antibodies." (PMID 38203686, 2023).
adenoma (4 papers, 2019 to 2025). A neoplasm arising from the epithelium. "Moreover, a correlation between IL1a and IL6 and VEGF expressed in 59 cultured adenoma cells was also found." (PMID 37958702, 2023).
Allergy (4 papers, 2010 to 2025). An allergy is an immune response or reaction to substances that are usually not harmful. "The present results showed an important association between SNPs in cytokine genes and susceptibility to or protection from allergy to dust mites in IL1A at position −889, IL4RA at position +1902, IL2 at positions −330 and +166, IL4 at position −590, and IL10 at position −592." (PMID 25238536, 2014). "The analysis implicated a number of genes with roles in allergy and inflammation, including pro-inflammatory cytokines (IL1A, IL1B, IL6, IL8 and TNF) and factors involved in immune cell activation and recruitment (SELE, SELL, SELP, ICAM1, CSF2, CSF3, CCL2 and CXCL2)." (PMID 21067579, 2010). "Therefore, we conclude that exposure to ozone exacerbates the detrimental effects on the integrity of the ocular surface caused by conjunctival allergic reactions, and further increases the inflammatory response in IL-1α-pretreated conjunctival epithelial cells." (PMID 28046113, 2017).